ZNF469 (zinc finger protein 469)
Diseases named in the same sentence as ZNF469 in open-access papers:
ZNF469 is named in the same sentence as 39 diseases in open-access papers, as found by Europe PMC text mining. Sharing a sentence is not in itself a finding about the gene and the disease. The quoted sentences say what the papers report.
brittle cornea syndrome (24 papers, 2010 to 2026). Brittle cornea syndrome is a form of Ehlers-Danlos syndrome characterized by a severe ocular manifestations due to extreme corneal thinning and fragility with rupture in the absence of significant trauma, and progression to blindness. "Transcriptional control of proteoglycan synthesis and ECM assembly is modulated by proteins produced by genes such as PRDM5 and ZNF469, both of which are associated with brittle cornea syndrome." (PMID 40981152, 2025). "Pathogenic variants in ZNF469 are associated with Brittle Cornea Syndrome (BCS1; OMIM 229200), a rare, autosomal recessive connective tissue disorder." (PMID 40156465, 2025). "Prior to this case series and the initial case report, variants in ZNF469 were only reported to be associated with the ocular disease brittle cornea syndrome (BCS)." (PMID 39769491, 2024). "Rare variants in the ZNF469 gene have been reported to be involved in the development of brittle cornea syndrome (BCS), which leads to thinning of the cornea and progressive visual impairment." (PMID 38267912, 2024). "Genes that stand out include VSX1 for its role in posterior polymorphous dystrophy (PPCD); ZNF469, implicated in brittle cornea syndrome and central corneal thinning (CCT); and DOCK9 or Zizimin1, associated with corneal ectasia." (PMID 37895187, 2023). "ZNF469 (OMIM:612078) in homozygosis is associated with brittle cornea syndrome type 1 (MIM:229200); however, heterozygous mutations in this gene have been found to cause keratoconus with autosomal dominant inheritance." (PMID 37895187, 2023). "Brittle cornea syndrome—Initially suspected to be a form of kEDS, brittle cornea syndrome (BCS) was demonstrated to be caused by biallelic pathogenic variants in either the ZNF469 or the PRDM5 gene." (PMID 35205310, 2022). "Recessively inheritedpathogenic variants in ZNF469 cause brittle cornea syndrome 1(BCS1; OMIM #229200), characterized by extreme thinning of the cornea and sclera.The ZNF469 c.6457G>A variant was predicted to be benign by allprediction programs used." (PMID 33645289, 2022). "Mutations in ZNF469 cause brittle cornea syndrome (BCS), a multisystem connective tissue disorder primarily associated with corneal thinning but also blue sclerae and joint hypermobility." (PMID 32671420, 2020). "After detection of the ZNF469 variants, the patients were closely reexamined for other typical features of brittle cornea syndrome (BCS)." (PMID 32671420, 2020). "ZNF469 has been proposed as a candidate gene for keratoconus, and its mutation is associated with brittle cornea syndrome." (PMID 31477016, 2019). "Brittle cornea syndrome is a generalized connective tissue disorder associated with ZNF469 and PRDM5 gene mutations." (PMID 26221552, 2015). "Brittle cornea syndrome is genetically heterogeneous and can be caused by mutations in either ZNF469 (MIM 612078) or PRDM5 (MIM 614161)." (PMID 23680354, 2013). "It is of particular interest that, while rare mutations in ZNF469 cause Brittle Cornea Syndrome, more common variants near this gene also contribute to CCT variation in the general population." (PMID 20485516, 2010). "The nearest gene to the associated chromosome 16 SNPs was ZNF469, a locus recently implicated in Brittle Cornea Syndrome (BCS), a very rare disorder characterized by abnormal thin corneas." (PMID 20485516, 2010). "Notably, COL5A1 and COL12A1 mutations underlie classical EDS, TNXB mutations cause a form of EDS with tenascin-X deficiency, and ZNF469 as mentioned is linked to brittle cornea syndrome (sometimes considered an EDS-like condition)." (PMID 41595486, 2026). "ZNF469 is thought to regulate extracellular matrix organization (possibly acting as a transcription factor affecting collagen genes), and mutations in ZNF469 cause extreme corneal thinning in brittle cornea syndrome." (PMID 41595486, 2026).
brittle cornea syndrome (continued). "HTRA3 (High temperature requirement A, Serine Peptidase 3) is a serine protease involved in matrix remodelling while ZNF469 (Zinc-finger protein 469) regulates the expression of extracellular matrix components and its mutations have been linked to brittle cornea syndrome." (PMID 40716152, 2025). "Rare variants in the ZNF469 gene (mutated in corneal dystrophy Brittle Cornea Syndrome) and in the TGFBI gene (mutated in multiple corneal epithelial–stromal TGFBI dystrophies) have been repeatedly identified in familial and sporadic KC patients of different ethnicities." (PMID 27350955, 2016). "The ZNF469 gene mutations at chromosome 14 are responsible for brittle cornea syndrome type 1." (PMID 26221552, 2015). "Evidence for ZNF469 includes strong human genetic support from syndromic disease (brittle cornea syndrome) and replicated GWAS signals, although enrichment of rare pathogenic variants in sporadic keratoconus remains inconsistent across cohorts." (PMID 41595486, 2026). "ZNF469 (which encodes a large zinc-finger protein) was initially known for its role in the recessive Brittle Cornea Syndrome, but a common SNP (rs9938149) near ZNF469/BANP also shows genome-wide significance for keratoconus and CCT." (PMID 41595486, 2026). "While previously unreported in PPCD3, ZNF469 critically regulates central corneal thickness (CCT), and its variants predispose to keratoconus and brittle cornea syndrome type 1." (PMID 40547359, 2025). "Despite pathogenic ZNF469 variants being associated with Brittle Cornea Syndrome (BCS), relatively little is known about ZNF469 beyond its participation in regulating the expression of genes encoding extracellular matrix proteins." (PMID 40156465, 2025). "The genes ZNF469 and PRDM5 each produce extracellular-matrix-related proteins that, when mutated, have been shown to result in the development of brittle cornea syndrome." (PMID 38892036, 2024). "Our group has recently identified that two genes, ZNF469 and PRDM5, previously only associated only with brittle cornea syndrome (BCS), are now associated with the development of aortic and arterial aneurysmal diseases (TAADs)." (PMID 38892036, 2024). "Homozygous mutations in ZNF469, another gene related to EDS, result in brittle cornea syndrome (BCS), which is characterized by extreme corneal thinning." (PMID 37374145, 2023). "Since brittle cornea syndrome is part of a generalized connective tissue disease, ZNF469 and PRDM5 gene products concern the development of extracellular matrix." (PMID 26221552, 2015). "The phenotypic spectrum of brittle cornea syndrome appears in an extremely similar, if not identical manner, in patients with mutations in either ZNF469 or PRDM5, suggesting that the two genes act within the same developmental pathway." (PMID 37443678, 2023). "In addition, the genes ZNF469 and PRDM5 have been previously associated with joint hypermobility but are mainly characterized by brittle cornea syndrome." (PMID 35886052, 2022).
keratoconus (20 papers, 2013 to 2026). A degenerative, structural disorder of the eye, characterized by a cone-shaped protrusion of the cornea. "The fact that the gene is mutated in the OFT-00242 family and the extensive literature on the correlation between variants in ZNF469 and the phenotype of keratoconus seem to suggest that the gene is involved in its development." (PMID 37895187, 2023). "A case has been reported where a male with a homozygous variant in the ZNF469 gene had brittle cornea syndrome, and his sons with the same variant in heterozygosis exhibited topographic indices compatible with keratoconus." (PMID 37895187, 2023). "A recent study proposed that heterozygous variants in PRDM5 and ZNF469 predisposed the patients toward the development of isolated keratoconus." (PMID 26489929, 2016). "In addition to ZEB1, variations in the ZNF469 gene have been implicated in keratoconus pathogenesis." (PMID 40547359, 2025). "ZNF469 alleles with low predicted pathogenicity were found to be enriched in 12.5% of keratoconus patients and could be a significant genetic risk factor for keratoconus." (PMID 37374145, 2023). "Similarly, other candidate genes identified by GWAS including HGF, RAB3GAP1, LOX, MPDZ, NFIB, BANP, and ZNF469 may be important risk factors for keratoconus and require replication studies in other populations." (PMID 25254113, 2014). "The overlap in corneal phenotype between BCS and keratoconus suggested ZNF469 as a candidate for the common form of KC." (PMID 41595486, 2026). "Variations of ZEB1 and ZNF469, which are identified in corneal dystrophy, have been suggested to be related to keratoconus." (PMID 40547359, 2025). "We anticipate that further research on ZNF469 and STON2 will reveal pleiotropic effects for these genes in terms of corneal thickness and the risk for keratoconus development." (PMID 32737415, 2020). "While early screenings for coding mutations in ZNF469 in sporadic KC were mostly negative some evidence indicates enrichment of rare ZNF469 variants in some keratoconus cohorts." (PMID 41595486, 2026). "Keratoconus is a progressive corneal disorder that may be associated with genetic factors, and new pathogenetic variants of ZEB1 and ZNF469 were identified in this study." (PMID 40547359, 2025). "It is probable that the similarities in the histopathology of brittle cornea syndrome and keratoconus could be due to the role of Znf469 in maintaining the corneal structure and thickness." (PMID 38067109, 2023). "Work remains to determine whether modulating ZNF469 activity will have therapeutic benefit in BCS or in conditions such as keratoconus in which the cornea thins progressively." (PMID 34368841, 2021). "However, the identified variants in these two zinc finger proteins might be in association with KC because variants in another zinc finger protein (ZNF469) were previously reported in association with keratoconus." (PMID 32887565, 2020). "A recent study utilized whole exome sequencing (WES) to identify 34 keratoconus-related genes and noted genetic variation for several genes that are pertinent to EDS, including COL5A1, TNXB, ZNF469, and COL12A1." (PMID 37374145, 2023). "Overall, we found a significant negative correlation of effect sizes across CCT and keratoconus (r = −0.62, P = 5.30 × 10−5), this correlation was largely unchanged if the known SNPs in ZNF469, FOXO1, COL5A1 and MPDZ/NFIB were removed from the analysis (r = −0.61, P = 2.04 × 10−4)." (PMID 29760442, 2018).
corneal dystrophies (4 papers, 2016 to 2025). "The ZNF469 gene was initially associated with central corneal thickness, which is abnormal in KTCN or corneal dystrophies and now is one of the most discussed KTCN genes." (PMID 32879808, 2020). "Our PPI network analysis also revealed interactions between ZNF469 and CCT candidate genes, including COL5A1, COL1A1, and other genes that regulate eyeball development, such as VSX1 (causing KC and corneal dystrophy) and CHST14 (Ehlers-Danlos Syndrome candidate gene)." (PMID 40547359, 2025).
breast carcinoma (3 papers, 2023 to 2025). "ZNF469 has the potential to provide a diagnostic and drug target for the prevention and treatment of breast cancer." (PMID 37736108, 2023). "We show a correlation between ZNF469 and breast cancer metastasis-related TF expression from RNA sequencing (RNA-seq) data of breast cancer in TCGA database." (PMID 37736108, 2023). "While the role of ZNF469 in breast cancer differentiation has not been previously investigated, we found that it promotes metastasis from tumor edge cells to malignant tumor cells via Rap1." (PMID 37736108, 2023).
glaucoma (3 papers, 2013 to 2018). Increased pressure in the eyeball due to obstruction of the outflow of aqueous humor. "Recent researches also confirmed that ZNF469 take an important role in anterior segment development and participate in pathogenesis of common ocular disorders such as glaucoma." (PMID 30227830, 2018).
liver fibrosis (2 papers, 2024 to 2025). "Overall, these data nominate ZNF469 as a previously unrecognized determinant of MASLD-associated liver fibrosis." (PMID 39998893, 2025). "Experiments of targeted loss-of-function/inhibition of ZNF469 in HSCs will be important to confirm its role in liver fibrosis." (PMID 39201329, 2024). "Recent computational profiling of the transcription factors associated with liver fibrosis from 108 human liver biopsies matched with transcriptomes and epigenomes identified ZNF469 as a transcriptional regulator of collagen production in HSCs." (PMID 39201329, 2024).
myopia (2 papers, 2016 to 2018). "However, in contrast to previous studies, recent sequencing analysis of ZNF469 in Polish patients with KC and high myopia and Polish individuals without ocular abnormalities found no significant enrichment of any sequence variants in ZNF469." (PMID 27350955, 2016).
aortic aneurysm (1 paper, 2024). A ruptured aneurysm located in the wall of the proximal portion of the descending aorta proceeding from the arch of the aorta. "This study, derived from genetic analysis of 135 subjects, is the first to report novel variants in the extracellular matrix regulatory gene, ZNF469 in a cohort of eight non-syndromic cases and a potential novel syndromic case of aortic aneurysms and/or arterial dissections among unrelated patients." (PMID 39769491, 2024).
Astigmatism (1 paper, 2013). A type of refraction error associated with abnormal curvatures on the anterior and/or posterior surface of the cornea. "No other family members had suffered corneal rupture, though her twin sister and younger brother (ZNF469 genotypes not tested) both wore spectacles for strabismus and astigmatism respectively and had blue sclerae and mild joint hypermobility." (PMID 23680354, 2013).
idiopathic pulmonary fibrosis (1 paper, 2026). Idiopathic pulmonary fibrosis (IPF) is a nonneoplastic pulmonary disease that is characterized by the formation of scar tissue within the lungs in the absence of any known cause. "Finally, we underscored the clinical relevance of ZNF469 by analyzing bulk and single-cell RNA sequencing data from patients with idiopathic pulmonary fibrosis and systemic sclerosis." (PMID 42206677, 2026).
kidney cancer (1 paper, 2024). Primary or metastatic malignant neoplasm involving the kidney. "Among these, ZNF469 mutations were found to be targeted by neoantigen-specific T-cells in a long-term responder to CIT, while ANKRD27 and OTOF were identified as potential tumor-specific antigens for liver and kidney cancer, respectively." (PMID 39238637, 2024).
lung carcinoma (1 paper, 2025). "From the validated three gene signature we focused on the two newly identified BACH1 target genes, HTRA3 and ZNF469, both of which are highly induced by BACH1 depletion in lung cancer cells." (PMID 40716152, 2025). "The signature works in most cells (but not in all), demonstrating that induction of HMOX1, ZNF469 and HTRA3 is a strong surrogate for BACH1 depletion in lung cancer cells and a good pan-tissue BACH1 signature." (PMID 40716152, 2025).
Pectus excavatum (1 paper, 2025). A defect of the chest wall characterized by a depression of the sternum, giving the chest ("pectus") a caved-in ("excavatum") appearance. "Two different missense variants in the ZNF469 gene classified as vous have been diagnosed in a patient with mitral valve anomaly, joint laxity, loose skin, and pectus excavatum." (PMID 41010011, 2025).
pulmonary fibrosis (1 paper, 2026). Chronic progressive interstitial lung disorder characterized by the replacement of the lung tissue by connective tissue, leading to progressive dyspnea, respiratory failure, or right heart failure. "Our findings collectively support a model wherein the TGF-β1/SMAD3/ZNF469 axis contributes significantly to ECM gene regulation and fibroblast activation, thereby positioning ZNF469 as a critical profibrotic factor and a promising therapeutic target in pulmonary fibrosis." (PMID 42206677, 2026).
triple-negative breast carcinoma (1 paper, 2025). An invasive breast carcinoma which is negative for expression of estrogen receptor (ER), progesterone receptor (PR), and human epidermal growth factor receptor 2 (HER2). "And high Linc-ZNF469–3 expression in triple-negative breast cancer (TNBC) cells promotes lung metastasis." (PMID 40510151, 2025).
tumor (7 papers, 2018 to 2024). "We verified that the less-studied ZNF469 was associated with poor tumor prognosis." (PMID 36077702, 2022). "Specifically, the hub upstream TF ZNF469 predicted by SDGs promotes immune escape to drive tumor growth and can serve as a potential immunotherapeutic target." (PMID 37736108, 2023). "Moreover, expression of ZEB1 and the long non-coding RNA (lncRNA) linc-ZNF469-3 were correlated with TNBC tumour recurrence." (PMID 35267409, 2022). "After adjusting the analysis by tumor purity, we found that the expression levels of COL1A2, COL1A1, COL3A1, ZNF469 and Periostin (POSTN) were significantly correlated with tumor purity in ESCA." (PMID 33543230, 2021).
cancer (4 papers, 2022 to 2025). A tumor composed of atypical neoplastic, often pleomorphic cells that invade other tissues. "Our analysis of the Cancer Genome Atlas (TCGA) cohort to assess the association of ZNF469 mutations with a prognosis in pan-cancer showed a higher ZNF469 expression and a poorer clinical prognosis in samples with ZNF469 mutations." (PMID 36077702, 2022). "Notably, seven UReg genes (GALNT14, KIAA0040, EPB41L1, ZNF469, BLNK, AK7, and WSCD1) are associated with the progression of various cancers in humans." (PMID 40241800, 2025).
connective tissue disorder (4 papers, 2013 to 2025). A disease involving the connective tissue. "A definitive diagnosis and differentiation from other connective tissue disorders can be established through genetic testing, which identifies mutations in the ZNF469 gene (Type 1) and PRDM5 gene (Type 2)." (PMID 40647596, 2025).
ZNF469 also shares sentences with these, for which no sentence is quoted: mastitis (2 papers); pancreatic cancer (2); aneurysmal diseases (1); blood disease (1); bovine tuberculosis (1); breast invasive carcinoma (1); Corneal astigmatism (1); COVID-19 (1); dysautonomia (1); Ehlers-Danlos syndrome (1); endolymphatic hydrops (1); Fuchs' endothelial dystrophy (1); hyperopia (1); Leber congenital amaurosis (1); lung adenocarcinoma (1); osteogenesis imperfecta (1); Strabismus (1); systemic sclerosis (1); thoracic aortic aneurysm (1); vasculopathy (1); Warburg micro syndrome (1).